EIF4EBP1 (eukaryotic translation initiation factor 4E binding protein 1)
Description:
Repressor of translation initiation that regulates EIF4E activity by preventing its assembly into the eIF4F complex: hypophosphorylated form competes with EIF4G1/EIF4G3 and strongly binds to EIF4E, leading to repress translation. In contrast, hyperphosphorylated form dissociates from EIF4E, allowing interaction between EIF4G1/EIF4G3 and EIF4E, leading to initiation of translation. Mediates the regulation of protein translation by hormones, growth factors and other stimuli that signal through the MAP kinase and mTORC1 pathways.
Synonyms: 4E-BP1; PHAS-I; 4EBP1; BP-1
Tractability: Small molecule: a structure with a bound ligand is known. PROTAC: UniProt records ubiquitination sites on it; ubiquitination databases record sites on it.
Target class: Other nuclear protein
Gene: Protein-coding gene on chromosome 8 (38,030,512 to 38,060,365, forward strand). Ensembl gene ENSG00000187840.
Subcellular location: Cytoplasm; Nucleus
Subcellular location (Human Protein Atlas): Cytosol; Nucleoplasm
Pathways (Reactome):
Metabolism of proteins: Activation of the mRNA upon binding of the cap-binding complex and eIFs, and subsequent binding to 43S
Signal Transduction: mTORC1-mediated signalling
Gene Ontology:
Molecular function: eukaryotic initiation factor 4E binding; protein binding; translation initiation factor binding; translation repressor activity
Biological process: G1/S transition of mitotic cell cycle; negative regulation of translation; negative regulation of translational initiation; positive regulation of mitotic cell cycle; TOR signaling
Cellular component: cytoplasm; cytosol; nucleoplasm; nucleus
Genetic constraint (gnomAD): Loss-of-function variants: 5 observed, 8.17 expected, observed/expected ratio (o/e) 0.61, 90% interval 0.32 to 1.28. That is too few expected variants to judge how well the gene tolerates losing a copy. Missense variants: 139 observed, 137.56 expected, observed/expected ratio (o/e) 1.01, 90% interval 0.88 to 1.16. Synonymous variants: 62 observed, 53.2 expected, observed/expected ratio (o/e) 1.17, 90% interval 0.95 to 1.44.
Homologues: Orthologues: macaque EIF4EBP1 (97% identical), dog EIF4EBP1 (95% identical), rabbit EIF4EBP1 (93% identical), guinea pig EIF4EBP1 (92% identical), mouse Eif4ebp1 (91% identical), pig EIF4EBP1 (82% identical), zebrafish eif4ebp1 (59% identical), rat Eif4ebp1 (51% identical), Drosophila melanogaster Thor (40% identical). Paralogues in human: EIF4EBP2 (58% identical), EIF4EBP3 (48% identical).
Diseases named in the same sentence as EIF4EBP1 in open-access papers:
EIF4EBP1 is named in the same sentence as 254 diseases in open-access papers, as found by Europe PMC text mining. Sharing a sentence is not in itself a finding about the gene and the disease. The quoted sentences say what the papers report.
breast cancer (132 papers, 2006 to 2025). A primary or metastatic malignant neoplasm involving the breast. "The overexpression of EIF4EBP1 is observed in multiple cancers such as hepatocellular and breast cancers and associated with poor prognosis of the patients." (PMID 35153752, 2021). "A previous study reported that loss of miR-125b is associated with increased EIF4EBP1 protein levels in breast cancers." (PMID 26646586, 2016). "The phosphorylation of the effector protein eukaryotic translation initiation factor 4E-binding protein 1 (4EBP1) within the PAM pathway is associated with poor prognosis in breast cancer and other malignancies due to the presence of elevated p4EBP1 levels in tumors." (PMID 39769140, 2024). "Along with RPS6KB2, high expression of EIF4EBP1 might be indicative of more aggressive breast tumor phenotypes as overexpression of EIF4EBP1 is associated with poor breast cancer prognosis." (PMID 35608730, 2022). "Furthermore, high EIF4EBP1 levels are associated with poor survival in all The Cancer Genome Atlas (TCGA) cancer entities combined, as well as in breast cancer, colorectal cancer, hepatocellular carcinoma or diffuse large B-cell lymphoma." (PMID 35228525, 2022). "However, the genomic locus for encoding EIF4EBP1 is amplificated, which results in overexpression of its corresponding mRNA in breast cancer, and the overexpressed mRNA is associated with poor prognosis of the patients." (PMID 25658620, 2015). "However, Karlsson and his colleagues demonstrated that EIF4EBP1 mRNA and total protein were associated with progression and poor prognosis in breast cancer, which is in agreement with our results in this study." (PMID 25658620, 2015). "EIF4EBP1 may be a key ARG associated with breast cancer survival." (PMID 33194339, 2020). "Based on the gene expression profile, EIF4EBP1 highly expressed in group B cancer, which has been reported to contribute for tamoxifen resistance in breast cancer." (PMID 41151488, 2025). "In breast cancer, EIF4EBP1 is highly overexpressed and frequently amplified, and is connected to increased metastasis, invasion, and tumor formation." (PMID 38202644, 2023). "Deregulation of the mTOR pathway (such as the overexpression of S6K1 and EIF4EBP1) is often found in human cancers (such as breast cancer) and promotes cell proliferation." (PMID 37686205, 2023). "The previous circRNA-miRNA-mRNA regulatory network showed has_circ_0000069-miR-125b-5p-EIF4EBP1 in the PPI network in breast cancer." (PMID 37303741, 2023). "EIF4EBP1 was reported to be overexpressed in a number of tumor entities in adults, including breast cancer, in which EIF4EBP1 is amplified as part of the 8p11–12 amplicon, as well as in ovarian and prostate cancer." (PMID 35379801, 2022). "On the other hand, EIF4EBP1, as part of the 8p11-12 amplicon, is frequently amplified in breast cancer." (PMID 35228525, 2022). "Some studies indicated that EIF4EBP1 is involved in the progression of various cancer types (including renal cell carcinoma, breast cancer) through regulating the transcription level of BRDT." (PMID 35186763, 2022). "Silence of EIF4EBP1 can significantly inhibit the proliferation of breast cancer cells by promoting G1 cell cycle arrest." (PMID 33435917, 2021). "As the malignancy of breast cancer increased, the expression of several ARGs, such as EIF4EBP1, FOS and TP63, decreased or increased." (PMID 33194339, 2020). "EIF4EBP1 had a higher expression level in patients with more malignant molecular subtypes and higher grade breast cancer." (PMID 33194339, 2020). "The overexpression of EIF4EBP1 is related to shorter recurrence-free survival in breast cancer patients." (PMID 32547955, 2020). "Eukaryotic Initiation Factor 4E-Binding Protein (EIF4EBP1, 4EBP1) is overexpressed in many human cancers including breast cancer, yet the role of 4EBP1 in breast cancer remains understudied." (PMID 31122207, 2019).
breast cancer (continued). "EIF4EBP1 is a candidate oncogene in breast cancer because it is commonly amplified and overexpressed, and is part of a genomic region that, when amplified, confers poor prognosis for patients." (PMID 31122207, 2019). "Because we saw only a small effect of everolimus on the proliferation of the ER- 8p11-p12 SUM-52 breast cancer cell line, we also wanted to test the effect of EIF4EBP1 knockdown on these cells." (PMID 31122207, 2019). "The frequency of EIF4EBP1 amplification across all breast cancer subtypes is approximately 13% according to data from The Cancer Genome Atlas (TCGA) and 14% according to data from the Molecular Taxonomy of Breast Cancer International Consortium (METABRIC)." (PMID 31122207, 2019). "EIF4EBP1 is located within the 8p11-p12 genomic locus, which is frequently amplified in breast cancer and is known to predict poor prognosis and resistance to endocrine therapy." (PMID 31122207, 2019). "Kaplan-Meier analysis of EIF4EBP1 expression in breast cancer patients demonstrated that overexpression of this gene was associated with reduced relapse free patient survival across all breast tumor subtypes." (PMID 31122207, 2019). "To determine the effect of directly targeting 4EBP1 in breast cancer cells, we first tested the two ER+ 8p11-p12 cell lines, SUM-44 and Cama-1, and used lentiviral vectors for two different shRNAs against EIF4EBP1." (PMID 31122207, 2019). "Therefore, the link of expression of EIF4EBP1 with resistance to Anthracycline-based neoadjuvant chemotherapy in patients with breast cancer should need further investigation." (PMID 41151488, 2025). "PSME2, MAPK10, EIF4EBP1 were screened as the prognostic genes in breast cancer." (PMID 37035151, 2023). "Furthermore, EIF4EBP1 acts as an oncogene in adenoid cystic carcinoma, bladder urothelial carcinoma, breast cancer (BRCA), KIRC, acute myeloid leukemia, liver hepatocellular carcinoma, lung adenocarcinoma, mesothelioma, and sarcoma." (PMID 35903358, 2022). "Since ETS1 and MYBL2 as well as EIF4EBP1 are overexpressed in other cancer entities, for instance in colorectal cancer or breast cancer, these transcription factors might also regulate EIF4EBP1 expression in cancers outside the CNS." (PMID 35228525, 2022). "Thus, lower expression of TSC1, along with higher expression of RPS6KB2 and EIF4EBP1, can be indicative of more aggressive breast cancer phenotypes." (PMID 35608730, 2022). "Also, EIF4EBP1 frequently increased in breast cancer, which is considered to be an indicator of poor prognosis and resistance to endocrine therapy." (PMID 35480110, 2022). "Among cohorts of patients with all sub-types of breast cancer, patients with higher expression (the higher quartile of the cohorts) of EIF4EBP1 and LSM1 mRNA had worse Relapse-Free Survival (RFS) than patients with lower expression of either genes, suggesting that the two genes act as oncogenes." (PMID 32987805, 2020). "Regarding prognosis, the two genes of the amplicon whose mRNA hyper-expression portends adverse relapse-free survival in breast cancer are EIF4EBP1 (Eukaryotic transcription initiation factor 4E binding protein 1) and LSM1 (LSM1 homolog, mRNA degradation associated)." (PMID 32987805, 2020). "Amplification of EIF4EBP1 leads to increased 4EBP1 expression and phosphorylation suggesting that mechanisms are in place to promote 4EBP1 mediated translation and post-translational regulation during breast cancer initiation and progression." (PMID 31122207, 2019). "Combined the finding in constructing ARG signature, EIF4EBP1 may be a key ARG for breast cancer." (PMID 33194339, 2020). "Breast cancer with 8p11.23 inhibition of the amplified EIF4EBP1 may increase the dependency of the cancer cells to the activity of mTOR in order to secure active protein production, and thus may make these cells sensitive to inhibition of mTOR by drugs such as everolimus." (PMID 32987805, 2020).
breast cancer (continued). "Quercetin suppresses the proteasome function in breast cancer cells, resulting in blocking MTOR activity by a decrease in the MTOR substrates EIF4EBP1/4E-BP1 and RPS6KB/p70S6 kinase phosphorylation, consequently triggering autophagy." (PMID 36497321, 2022). "Using univariate Cox regression analysis, a total of 4 autophagy-related genes (EIF4EBP1, IFNG, NRG1, TP63) were significantly correlated with overall survival (OS) of breast cancer." (PMID 35480110, 2022). "We also found that our deep-learning classifier predicted well (AUC > 0.65) on the CNA status in breast cancer, including six genes of FGFR1, EIF4EBP1, KAT6A, HEY1, ZNF217, and RAB25." (PMID 34556802, 2021). "Another eight ARGs (BCL2, BIRC5, EIF4EBP1, ERO1L, FOS, GAPDH, ITPR1, and VEGFA) were explored, and the author found that these genes not only were significantly associated with overall survival but also could predict distant metastasis-free survival in breast cancer." (PMID 34869345, 2021). "Recently, on the basis of the GEO database, Gu and his colleagues constructed an ARG model consisting of eight genes (BCL2, BIRC5, EIF4EBP1, ERO1L, FOS, GAPDH, ITPR1, and VEGFA), which can be used as an independent prognostic indicator of breast cancer." (PMID 32649310, 2020). "Additionally, hypoxia inhibits protein synthesis through a pathway involving eukaryotic translation initiation factor 4E-binding protein 1 (4E-BP1) and elongation factor 2 kinase, controlled by mTOR and uncoupled in breast cancer cells." (PMID 39494346, 2024). "Over-expression of RPS6KB2 and EIF4EBP1 and under-expression of TSC1 might be indicators of more aggressive breast cancer phenotypes." (PMID 35608730, 2022). "EIF4EBP1 may be a key ARG which had a higher expression level in patients with more malignant molecular subtypes and higher grade breast cancer." (PMID 33194339, 2020).
prostate carcinoma (32 papers, 2013 to 2025). A carcinoma that arises from epithelial cells of the prostate gland. "On the one hand, loss of EIF4EBP1 and low 4EBP1 levels have been linked to poor survival of patients with head and neck squamous cell carcinoma or prostate cancer." (PMID 35228525, 2022). "High level of EIF4EBP1 phosphorylation is associated with malignant progression and adverse prognosis in several malignancies, such as breast, ovary and prostate cancers." (PMID 32684843, 2020). "So far, only a few transcription factors have been characterized to promote EIF4EBP1 transcription in other tumor entities, including the androgen receptor in prostate cancer, ETS1 and MYBL2 in glioblastoma, and MYCN in neuroblastoma." (PMID 40670359, 2025). "Additionally, MYC was shown to directly control EIF4EBP1 transcription in colon adenocarcinoma and prostate cancer cells, supporting that EIF4EBP1 represents a MYC target gene." (PMID 40670359, 2025). "This expands previous studies reporting on the control of EIF4EBP1 transcription by MYC in colorectal and prostate cancer cells." (PMID 40670359, 2025). "Moreover, EIF4EBP1 and RPS6KB1 showed a positive correlation with the catalytic subunit METTL3 in prostate cancer and contained candidate sites for m6A modifications (Supplementary Excel S6), suggesting m6A involvement in their translation." (PMID 33273988, 2020).
glioma (30 papers, 2011 to 2025). A benign or malignant brain and spinal cord tumor that arises from glial cells (astrocytes, oligodendrocytes, ependymal cells). "Moreover, we showed that high expression of EIF4EBP1 (the gene encoding 4EBP1) is a factor of poor prognosis in glioma and glioblastoma." (PMID 38744825, 2024). "Collectively, our data highlight that EIF4EBP1 is linked to malignancy and poor outcome in various human tumor types, including glioma, and that 4EBP1 exerts a pro-tumorigenic function in glioblastomas by reducing ACC1 expression." (PMID 38744825, 2024). "We found seven transcription factor candidates co-expressed with EIF4EBP1 in gliomas and bound to the EIF4EBP1 promoter, as revealed by chromatin immunoprecipitation (ChIP)-sequencing data." (PMID 35228525, 2022). "Here, we analyzed EIF4EBP1 expression in different glioma patient cohorts and investigated its mode of transcriptional regulation in glioblastoma cells." (PMID 35228525, 2022). "We also investigated the potential association of EIF4EBP1 expression with the IDH mutation status in primary glioma samples and found that EIF4EBP1 mRNA expression is not dependent on the IDH mutation status in three independent datasets." (PMID 35228525, 2022). "By bioinformatic analysis, we identified seven transcription factors that may potentially drive overexpression of EIF4EBP1 in gliomas." (PMID 35228525, 2022). "We searched for transcription factors that are positively co-expressed with EIF4EBP1 in gliomas and found EIF4EBP1 mRNA expression to be significantly and positively associated with the mRNA expression levels of MYBL2, FOXM1, ETS1, HIF-1A, JUN, E2F1, and E2F6 in the REMBRANDT dataset." (PMID 35228525, 2022). "Exposure of human high-grade glioma cells to soluble neuroligin 3 secreted by active neurons results in increased phosphorylation of eukaryotic translation initiation factor 4E-binding protein 1 (4E-BP1), which is an mTOR downstream effector." (PMID 33281551, 2020). "Given the clinical relevance we uncovered for EIF4EBP1 mRNA and 4EBP1 protein expression in MB patients, we wondered whether 4EBP1 contributes to cell migration and exerts a pro-tumorigenic function in this tumor entity, as reported in gliomas and Ewing sarcomas." (PMID 40670359, 2025). "Within different glioma types, EIF4EBP1 expression is found to be higher in the most aggressive CNS World Health Organisation (WHO) grade 4 glioblastoma, followed by grade 3 and grade 2 gliomas." (PMID 38744825, 2024). "Based on a glioma dataset from TCGA database, a recent study reported on overexpression of EIF4EBP1 in glioblastoma tissue samples compared to non-neoplastic brain tissues." (PMID 35228525, 2022).
glioblastoma (27 papers, 2010 to 2026). The most malignant astrocytic tumor (WHO grade IV). "In summary, we elucidated molecular mechanisms of enhanced EIF4EBP1 levels in glioblastoma cells, revealing the oncogenic transcription factors ETS1 and MYBL2 as responsible transcriptional regulators." (PMID 35228525, 2022). "We observed that E2F6 knock-down in U-87 MG and U-118 MG had no impact on 4EBP1 mRNA and protein levels, eliminating E2F6 as a transcriptional regulator of EIF4EBP1 in these glioblastoma cell lines." (PMID 35228525, 2022). "Based on these results, we identified two transcription factors, ETS1 and MYBL2, that regulate EIF4EBP1 expression in glioblastoma cells." (PMID 35228525, 2022). "We found that EIF4EBP1 is overexpressed in glioblastoma tissue samples in different patient cohorts as compared to non-neoplastic brain tissues, thus extending previous observations made in the TCGA cohort." (PMID 35228525, 2022). "We showed with promoter-reporter assays and genetic knockdown experiments that among these factors, ETS1 and MYBL2 regulate EIF4EBP1 transcription in IDH-wildtype glioblastoma cells." (PMID 35228525, 2022). "Taken together, this raises the possibility that the induction of EIF4EBP1 expression by ETS1 and MYBL2 in glioblastoma cells may be a previously unrecognized mechanism mediating angiogenesis in this tumor type." (PMID 35228525, 2022). "These analyses indicate that the co-expression between MYBL2 and EIF4EBP1 is not restricted to glioblastomas, suggesting that MYBL2 might represent a more general regulatory mechanism driving EIF4EBP1 expression in different cancer entities." (PMID 35228525, 2022). "Finally, we analyzed existing ChIP-sequencing (seq) data from the Encode consortium, which demonstrated direct binding of FOXM1, ETS1, E2F1, and E2F6 to the EIF4EBP1 promoter region, exon 1 and intron 1 (−1500 to +1000) in various normal and cancer cells, however not including glioblastoma cells." (PMID 35228525, 2022). "We verified that EIF4EBP1 mRNA is overexpressed in malignant gliomas, including isocitrate dehydrogenase (IDH)-wildtype glioblastomas, relative to non-neoplastic brain tissue in multiple publically available datasets." (PMID 35228525, 2022). "Specifically, we analyzed EIF4EBP1 mRNA expression levels in EGFR-amplified and EGFR-non-amplified as well as in O6-methylguanine DNA methyltransferase (MGMT) promoter-methylated and promoter-unmethylated IDH-wildtype glioblastoma patient samples using publically available datasets." (PMID 35228525, 2022). "Interestingly, we observed that EIF4EBP1 mRNA expression is tightly correlated with 4EBP1 phosphorylation level in glioblastoma, suggesting that in glioblastoma higher phosphorylated 4EBP1 results from EIF4EBP1 overexpression and therefore does not indicate increases of inactive 4EBP1." (PMID 38744825, 2024).
lung carcinoma (26 papers, 2012 to 2025). "Interestingly, we found that ARHGs with active copy number increase (e.g. MYC, EIF4EBP1, EGFR) and ARHGs with active copy number loss (e.g. ATG16L1, MTOR, ULK1) also showed high expression in lung cancer tissues." (PMID 35333893, 2022).